PDCD1 (programmed cell death 1)
Diseases named in the same sentence as PDCD1 in open-access papers (continued):
Sharing a sentence is not in itself a finding about the gene and the disease.
cancer (continued). "In patients with advanced, refractory cancer, autologous NY-ESO-1 TCR–engineered T cells in patients after CRISPR–Cas9 editing of the TRAC, TRBC, and PDCD1 loci were infused with lasting persistence for 9 months." (PMID 38609863, 2024). "Compared to cluster 4, cluster 2 cells showed higher expression of SLAMF7, ZEB2, GZMB, GPR18, CD72, PDCD1 (PD1) and CRTAM that are known to be expressed in terminally differentiated effector cells in viral infections and various cancers." (PMID 38501302, 2024). "The findings revealed that 22 genes, including key immune checkpoint molecules such as PDCD1, TIGIT, and LAG-3, were significantly upregulated in hot tumors across all five cancer types." (PMID 39911580, 2024). "The Tfh cell markers PDCD1 and CXCR5 were decreased during the carcinoma progression, which is consistent with the change of t peripheral Tfh population." (PMID 38343544, 2024). "Programmed cell death 1 (PD-1)/programmed death ligand 1 (PD-L1), a representative ICB, has initiated a new era in cancer treatment." (PMID 37344841, 2023). "The researchers used CRISPR–Cas9 to knock out three genes (TRAC, TRBC, and PDCD1) from the patients' T cells, and such modified T cells (CAR‐T cells) were reinfused into three patients with refractory cancer." (PMID 36925702, 2023). "The expression of ICOS mediates infiltration of immune cells and is positive correlated with the expression of PDCD1, CTLA4, and TIGIT in most cancer types." (PMID 36855091, 2023). "In contrast, cancer immunotherapy can recover the normal body’s function of antitumor immune response via regulating the expression of checkpoint genes, such as TNFSF9, PDCD1 and CTLA4." (PMID 37013511, 2023). "Antibodies targeting PD-1 (programmed cell death 1, also known as PDCD1) and PD-L1 (PDCD1 ligand 1, also known as B7H1 and CD274) are promising strategies in many cancer types, including colorectal cancer." (PMID 37875976, 2023). "We found that PTPN6 expression was positively correlated with PDCD1, CD274, CTLA4, LAG3, HAVCR2, and CD244 in most cancer types in TCGA, including LGG and GBM." (PMID 37737713, 2023). "Recently, immunotherapy, such as immune-checkpoint blockade programmed cell death 1 (PD-1) and programmed cell death 1 ligand 1 (PD-L1), has further improved the prognosis of patients with CRC, especially those with late-stage cancer." (PMID 37596528, 2023). "A recent study shows the significant power of a model combining gene expression of immune-related genes, including CD274 and PDCD1, and the TMB to identify pan-cancer ICI-treated patients that will have a longer PFS and OS39." (PMID 37430006, 2023). "For instance, ICOS has positive relationships with PDCD1, TIGIT, CD274, and CTLA4 in the majority of cancer types, indicating a broad co-expression landscape." (PMID 36855091, 2023). "We analyzed the expression profile of COMMD2 gene and ICGs (CD274, CTLA4, HAVCR2, LAG3, PDCD1, PDCD1LG2, SIGLEC15, and TIGIT) at a pan‐cancer level." (PMID 36205192, 2023). "mAbs targeting CTLA4, PDCD1, CD274, and LAG3 have been approved by the FDA for second- and first-line treatment against cancer, whereas mAbs targeting ICOS and CD40 are under investigation." (PMID 37215135, 2023). "Therapy with blocking programmed cell death 1 (PD-1), PD-1 ligand 1 (PD-L1), and cytotoxic T lymphocyte antigen-4 (CTLA-4) becomes promising approach for cancer treatment." (PMID 37258621, 2023). "To date, four anti-PDCD1 mAbs have been approved by FDA and/or EMA for different cancer types, nivolumab (OPDIVO®, mAbID 424), pembrolizumab (KEYTRUDA®, mAbID 472), dostarlimab (JEMPERLI, mAbID 849) and cemiplimab (LIBTAYO®, mAbID 846)." (PMID 37215135, 2023). "The novel immunotherapy agents such as inhibitors of PDCD1, TIGHT, IDO1, CD274, CTLA4 and LAG3 were considered had potential survival benefit in several cancers." (PMID 37608927, 2023). "Studies show that immune checkpoints TDO2, PDCD1, LGALS9, and PVR play an important role in cancer treatment and prognosis." (PMID 36686663, 2022).
cancer (continued). "Immune checkpoint inhibitors (ICI), for instance, programmed cell death 1 (PD-1), programmed cell death ligand-1 (PD-L1), cytotoxic T lymphocyte antigen 4 (CTLA-4) have shown notably promise for the treatment of various cancers." (PMID 35669769, 2022). "Here, we evaluated the correlation between three classic ICGs, CD274, CTLA4 and PDCD1, and MCM2 expression in 40 TCGA cancers." (PMID 35693940, 2022). "The discovery of immune checkpoint inhibitors, which target the programmed cell death 1(PD-1), programmed cell death ligand (PDL1), and cytotoxic T lymphocyte antigen 4 pathways, has resulted in the development of new cancer therapies." (PMID 36100891, 2022). "Among cancer immunotherapy, immune checkpoint blockade (ICB), which targets cytotoxic T lymphocyte antigen 4 (CTLA4) or the programmed cell death 1 (PD1)-ligand 1 (PD­ L1) axis has been approved for treating many different cancers." (PMID 36109526, 2022). "Our results demonstrated the significantly negative correlations of m7Gscore with the expression of IDO1, PDCD1, and LAG3, which have been considered as important targets for cancer immunotherapy." (PMID 36246663, 2022). "In recent years, the discovery of the immune checkpoints, such as programmed cell death 1(PD-1) and cytotoxic T lymphocyte antigen 4 (CTLA-4), has also greatly changed treatment methods and ideas for malignant tumors." (PMID 36159861, 2022). "The key immune checkpoints (CD274, CTLA-4, HAVCR2, LAG3, PDCD1, PDCD1LG2, SIGLEC15, and TIGIT) also had a significant relationship with DTYMK expression in approximately 20 kinds of cancers, except in MESO, PCPG, and UCS." (PMID 36094557, 2022). "The application of immune checkpoint inhibitors (ICIs), targeting the programmed cell death 1 (PD-1)/programmed cell death ligand 1 (PD-L1) and cytotoxic T-lymphocyte antigen 4 (CTLA-4) pathways, holds immense promise for cancer treatment." (PMID 35740355, 2022). "Finally, germline polymorphisms of the genes encoding relevant immune checkpoints (CTLA4, PDCD1, and PDL1) have been implicated in cancer risk, with signals from small retrospective studies starting to emerge that particular alleles may also associate with ICI benefit." (PMID 35394069, 2022). "Immune checkpoint inhibitors (ICIs) targeting programmed cell death 1 (PD-1), programmed cell death ligand 1 (PD-L1), and cytotoxic T lymphocyte antigen 4 (CTLA-4) have become a well-established therapeutic option for cancer." (PMID 36484006, 2022). "ICIs target immune system activation against cancer cells; specifically, these monoclonal antibodies are cell surface proteins (i.e., cytotoxic T-lymphocyte antigen-4 [CTLA-4]) and programmed cell death-1 (PD-1)/programmed cell death ligand-1 (PD-L1)." (PMID 36341419, 2022). "After that, we compared the expression of cancer biomarkers ATM, BRCA1, PDCD1, and EGFR gene in the two groups." (PMID 36226174, 2022). "Phagocytosis checkpoints, including PDCD1, LILRB1, SIGLEC10, and SIRPα are significantly for the function of TAMs in many cancers." (PMID 35317832, 2022). "Correlation analysis of FDX1 with checkpoint gene expression found a high correlation (p < 0.05) with tumor necrosis factor (TNF)–related immune genes (TNFRSF14, 15, 25) and CTLA4, PDCD1, CD274, NRP1, and VTCN1 in some kinds of cancers." (PMID 36061184, 2022). "Our results suggested that in most types of cancer, SERCA3 expression was distinctly related to immune checkpoints, such as TLR4, ICOS, CTLA-4, PDCD1, and CD27." (PMID 36385955, 2022). "In conclusions, the results of the present study revealed that the role of Pdcd1 in DOX-induced apoptosis is opposite between cardiomyocytes and cancer cells." (PMID 35190965, 2022). "Among the 5,343 identified general translocations, ~200 genes involved in various cancer pathways were observed to fuse with the TRAC, TRBC, or PDCD1 gene." (PMID 35260581, 2022).
cancer (continued). "In particular, three immune checkpoint pathways, namely programmed cell death-1 (PD-1), programmed cell death-ligand 1 (PD-L1) and cytotoxic T-lymphocyte antigen 4 CTLA-4, have emerged as target for cancer therapeutics." (PMID 36497292, 2022). "However, the apoptotic mechanisms of Pdcd1 overexpression in cancer cells remain unclear." (PMID 35190965, 2022). "In a human cancer mouse model, oral administration of the TTK inhibitor cfi-402257 alone or in combination with an anti-programmed cell death 1 (PD-1) antibody inhibited tumor growth at a well-tolerated dose." (PMID 35784389, 2022). "Other potential immune checkpoints, such as LAG3, CD96, PDCD1, BTLA, IDO1, and TIGIT, were also enriched in PTPRD/PTPRT mutant cancers." (PMID 36248841, 2022). "Afterward, we evaluated the link between DTYMK expression and key immune checkpoints (CD274, CTLA-4, HAVCR2, LAG3, PDCD1, PDCD1LG2, SIGLEC15, and TIGIT) expression levels in pan-cancer." (PMID 36094557, 2022). "Pdcd1 signaling prevented DOX-induced apoptosis in cardiomyocytes, through autophagy induction; it enhanced DOX-induced apoptosis in cancer cells." (PMID 35190965, 2022). "AP3S1 expression was positively correlated with most immunosuppressive genes in pan-cancer, such as the common CD274 (PD-L1), PDCD1 (PD-1), CTLA4, LAG3, and TIGIT." (PMID 35874816, 2022). "Successful treatment of many cHL patients using antibodies against programmed cell death 1 (PD-1; known as PDCD1) and its ligand (PD-L1; known as CD274) has highlighted the critical importance of PD-1/PD-L1-mediated immune escape in cancer development." (PMID 36140254, 2022). "Thus, the role of Pdcd1 in cancer cells could be different from that in cardiomyocytes." (PMID 35190965, 2022). "The therapeutic targeting of immune checkpoints has attracted considerable attention in cancer immunotherapy, particularly concerning CTLA-4 and programmed cell death 1 (PD-1)." (PMID 35893056, 2022). "On tumor cells, the interaction between programmed death 1 receptor (PD-1, PDCD1) and its ligand programmed death-ligand 1 (PD-L1, CD274) is a critical immunosuppressive mechanism in cancer." (PMID 36230513, 2022). "Immune checkpoint blockade (ICB) therapies, including inhibition of programmed cell death 1 (PD-1) or ligand 1 (PD-L1) and cytotoxic T-lymphocyte antigen-4 (CTLA-4), have been able to induce a lasting response across multiple cancer lineages." (PMID 36273184, 2022). "Recent progress in the development of immune checkpoint inhibitors, such as anti-programmed cell death-1 (PD-1) antibodies and chimeric antigen receptor (CAR) T cells, holds promise for the treatment of various cancer types." (PMID 33128583, 2021). "The results revealed that PDCD1, IDO1, and CTLA4 were significantly upregulated in cluster 3 patients compared with cluster 1 patients in multiple cancer types." (PMID 33627136, 2021). "This exploratory study uses a bioinformatic approach to examine the impact of mRNA levels of PDCD1, CD274, and genes showing correlated expression levels on the survival outcome of a range of cancers." (PMID 34067485, 2021). "The results revealed that CD161 was positively correlated with marker genes of exhausted T cells, immune activating genes, and immunosuppressive genes in pan-cancer, such as TIGIT, PDCD1, LAG3, CTLA4, STING1, CD96, and IDO1." (PMID 34305920, 2021). "Forty genes were consistently correlated with PDCD1/CD274 across multiple cancers, with the cancers themselves exhibiting a differential role for the correlated genes in terms of patient survival." (PMID 34067485, 2021). "We found that the expression level of GRWD1 was positively correlated with the expression levels of immune checkpoint-related genes (CD274, CTLA4, HAVCR2, LAG3, PDCD1, PDCD1LG2, SIGLEC15, and TIGIT) in most types of cancer, especially in STAD." (PMID 34616846, 2021).
cancer (continued). "This bioinformatic study interrogated molecular differences pertaining to PDCD1/CD274 and their correlated genes on a pan-cancer basis to identify differences between cancer types." (PMID 34067485, 2021). "TIGIT expression mediated infiltrated immune cells and positively correlated with the expression of LAG3, CTLA4, PDCD1 (PD-1), CD274 (PD-L1), PDCD1LG2 (PD-L2) in most of the cancer types." (PMID 34795387, 2021). "We found that CD161 was positively correlated with marker genes of exhausted T cells, immune activating genes, and immunosuppressive genes in pan-cancer such as TIGIT, PDCD1, LAG3, CTLA4, STING1, CD96, and IDO1." (PMID 34305920, 2021). "TIGIT expression also positively correlated with CTLA4, PDCD1 (PD-1), CD274 (PD-L1), ICOS in most of the cancer types." (PMID 34795387, 2021). "Immune checkpoints like CTLA4, CD274 (PD-1), and PDCD1 (PD-L1) were highly expressed in high-CD3E and high-LCK groups for MIBC and also for pan-cancers, except for thymoma." (PMID 35004669, 2021). "Checkpoint blockade cancer immunotherapies such as cytotoxic T lymphocyte antigen 4 antibody (anti-CTLA-4) and programmed cell death 1 antibody (anti-PD-1) were also demonstrated for clinical applications." (PMID 32116701, 2020). "Since co-inhibitory receptors, such as PDCD1 and TIGIT, are targets for cancer immunotherapies, we then focused on analyzing the preferential enrichment of exhausted CD8+ T cells in GC." (PMID 32039830, 2020). "With regard to the fact that as far as we know in the literature there is no published data regarding associations of PDCD1 and PD-L1 polymorphisms with ccRCC risk and outcomes, we believe that our research will broaden current knowledge of the genetic basis of this type of cancer." (PMID 33255938, 2020). "Anti–programmed cell death 1 (PD-1) antibodies, an immune checkpoint inhibitor (ICI), exert antitumor effects by suppressing the immune tolerance to cancer cells." (PMID 33180128, 2020). "Recently, immunotherapy target the programmed cell death 1 programmed cell death 1 (PD-1), PD-1 ligand (PD-L1), cytotoxic T-lymphocyte antigen-4 (CTLA-4) offers great promise for various cancer therapies 4-6." (PMID 31929742, 2020). "Simultaneous overexpression of PDCD1 and PDCD1LG1 in a subpopulation of cancer cells can inhibit cell proliferation and signaling transduction." (PMID 32516941, 2020). "PRDM1 expression positively correlates with the expression of LAG3, CTLA4, PDCD1 (PD-1), CD274 (PD-L1), PDCD1LG2 (PD-L2), TIGIT in the majority of 33 cancer types." (PMID 33384601, 2020). "Approximately 3.8–29.4% of cancer patients and 13.8–37% of advanced non-small cell lung cancer (NSCLC) patients under anti-programmed cell death 1/ programmed death ligand 1 (PD-1/PD-L1) inhibitors, reported HPD." (PMID 36046388, 2020). "Cancer cells regularly harness CTL antigen 4 (CTLA-4 or CD152) and programmed cell death-1 (PD-1 or CD279) immune-checking molecules to escape detection and elimination by the immune system." (PMID 31694270, 2019). "Remarkably, TRM cells infiltrating human NSCLC tumors also express inhibitory receptors such as programmed cell death-1, the neutralization of which, with blocking antibodies, enhances CD103-dependent TCR-mediated cytotoxicity toward autologous cancer cells." (PMID 30158938, 2018). "Of the non-T-cell related targets, the proteins currently most widely targeted are ERBB2 (HER2), EGFR, MS4A1 (CD20), CD22, PDCD1 (PD-1), MSLN (mesothelin), and ERBB3 (Her3), all for cancer indications." (PMID 28822103, 2018). "Over the past few decades, immune checkpoint inhibitors (ICIs), which are antibodies that target inhibitory immune checkpoint molecules such as programmed cell death-1 (PD-1), programmed cell death ligand-1 (PD-L1), and cytotoxic T-lymphocyte antigen-4 (CTLA-4), have revolutionized cancer treatment." (PMID 39949779, 2025).
cancer (continued). "However, each gene in different cancers positively correlated (p < 0.05) with either its mRNA expression or CNVs, e.g., TIGIT in ACC, LAG3 in UVM, HAVCR2 in LUSC, LAYN in OV and PDCD1 in BLCA." (PMID 40076932, 2025). "Furthermore, in pan-cancer, TRPM6 was negatively correlated with CD274, LAG3, PDCD1, and SIGLEC15, and showed significant differences (P < 0.01)." (PMID 41562086, 2025). "Notably, in cancers such as COAD, BRCA, LUAD, READ, and CESC, tumors in the low-succinylation group exhibited elevated expression levels of PDCD1 (PD-1), CD274 (PD-L1), and CTLA4 at both the transcriptional and protein levels." (PMID 40463370, 2025). "PDCD1 (PD-1), a central marker of TEX, is upregulated in chronic viral infections and cancers." (PMID 41009979, 2025). "Autologous T cells collected from three cancer patients were modified using Cas9 RNPs targeting TRAC, TRBC, and PDCD1 genes and further engineered with a lentivirus carrying an HLA‐A2*0201‐restricted TCR specific to cancer antigens NY‐ESO1 and LAGE‐1 to generate engineered T cells, called NYCE." (PMID 39156766, 2024). "Interactions of several ligand-receptor pairs between cancer cells and immune cells (CD274:PDCD1, FAM3C:PDCD1, PVR:TIGIT) are predicted to be enhanced in NRF2 signature high samples which could be potential targets to inhibit to remodel the TME." (PMID 38241355, 2024). "Additionally, it was illustrated that ANKRD27 expression showed a positive correlation with the level of inhibitory immune checkpoints, such as CD274, PDCD1, CTLA4, and HAVCR2, across various types of cancer." (PMID 39834932, 2024). "Furthermore, this system can be used to evaluate the sensitivity of cancers in individual patients to immunotherapies targeting cytotoxic CD8+ T cells, such as monoclonal antibodies against PD-1 (also known as PDCD1) and PD-L1 (or CD274)." (PMID 38258518, 2024). "Our analysis indicates that PDCD1 expression was not high in the majority of the cancers, apart from KIRC." (PMID 39064019, 2024). "Overall, immune checkpoint expression may be dysregulated in the HCC microenvironment, and cancer immunotherapy based on CTLA-4, PDCD1 and PD-L1 inhibitors may achieve antitumor therapeutic effects by improving Treg cell-mediated immune responses." (PMID 37426702, 2023). "Immune checkpoint inhibitors, such as those targeting cytotoxic T lymphocyte‐associated molecule 4 (CTLA‐4), programmed cell death receptor 1 (PDCD1, also named PD‐1), and programmed cell death ligand 1 (CD274, also named PD‐L1), have revolutionized cancer treatment." (PMID 37904707, 2023). "In recent years, immune checkpoint blocking (ICB) therapy, specifically antibodies against programmed cell death 1 (PD1)/ programmed cell death-Ligand 1 (PD-L1) signaling, has been widely used in cancer, which greatly prolongs the survival time of cancer patients." (PMID 36932387, 2023). "In addition, we also itemized the correlations between TAGLN2 and the major immune checkpoints in pan-cancer, including LAG3, PDCD1, CTLA4, CD274, and TIGIT." (PMID 37476180, 2023). "Among the immune evasion mechanisms of cancer cells, the interaction between programmed cell death 1 (PD1) and programmed death-ligand 1 (PD-L1) is critical and important in cancer treatment because immune checkpoint inhibitors targeting PD1/PD-L1 show therapeutic efficacy." (PMID 37761326, 2023). "Thus, six major ICs for cancer immunotherapy were analyzed in this work, namely CTLA4, PDCD1, CD274, ICOS, LAG3, and CD40." (PMID 37215135, 2023). "Therefore, the application of anti-CTLA4, anti-PDCD1 (PD-1) and anti-CD274 (PD-L1) agents is becoming a promising therapeutic option in several types of cancers." (PMID 36845098, 2023). "PDCD1, TGFB1, CXCL8, CCL3, CCL4, and CCL5 were highly expressed in subTME-IS; CXCL2 and CXCL12 were highly expressed in subTME-ICI, which was consistent among cancer types." (PMID 38002057, 2023).